ABCG2 (ATP binding cassette subfamily G member 2 (JR blood group))
Diseases named in the same sentence as ABCG2 in open-access papers (continued):
Sharing a sentence is not in itself a finding about the gene and the disease.
breast cancer (continued). "Another tumor-related marker that is up-regulated in pathological ECs vs. healthy ECs is ABCG2, a multidrug-resistance receptor (MDR) in breast cancer cells that is also expressed by various ECs." (PMID 34445568, 2021). "Of note, ABCG2 mRNA and/or protein expression were related to breast cancer side population (SP) cells in the MCF7 and MDA-MB-231 breast cancer cell lines." (PMID 33801148, 2021). "In this study, we report that the expression levels of ID4 appeared to correlate with breast cancers subtype differentiation biomarkers (including ER, PR) and chemo-resistance related proteins (including MRP1, ABCG2, P-gp)." (PMID 32328189, 2020). "First, we evaluated the ALDH activity, the expression of BCSC genes (Nanog, Sox2 and Oct4), multiresistance pumps (ABCG2, ABCC1 and ABCB1) and the BCSC frequency (CD44+CD24+CD49+EPCAM+) in three human breast cancer cell lines." (PMID 33184339, 2020). "ABCG2, as an important member of the ABC transporter superfamily, has been thoroughly studied since its first isolation from drug-resistant human breast cancer cell lines." (PMID 32085398, 2020). "In the same manuscript, three N-alkylated 3-aminochalcones were also synthesized and discussed for their ability to selectively inhibit P-glycoprotein (Pgp; ABCB1) and breast cancer-resistant protein (BCRP; ABCG2)." (PMID 33213087, 2020). "Breast cancer resistance protein (BCRP, ABCG2) was first cloned from a breast cancer cell line resistant to chemotherapeutic agents." (PMID 33198344, 2020). "A recent report showed that LEF1 and multidrug resistance-related genes, such as ABCG2, VIM, and Cav1, are highly increased in docetaxel (DTX)-resistant MCF7 breast cancer cells, indicating that LEF1 is involved in multidrug resistance in cancer." (PMID 32933177, 2020). "The human breast cancer resistance protein (BCRP/ABCG2), which was derived from the breast cancer cell line Mcf-7, was shown to induce resistance to mitoxantrone." (PMID 31709180, 2019). "In particular, multidrug-resistant protein-1 (ABCC1/MRP1), breast cancer resistance protein (ABCG2/BCRP) and multidrug-resistant protein-8 (ABCC11/MRP8) were expressed significantly more, and more frequently in TNBC compared to other breast cancer subtypes." (PMID 31443516, 2019). "Statistical analysis of IHC data of 72 human breast cancer samples revealed a high correlation between GHR (40%), pAKT (73%), and pmTOR (75%) with ABCG2." (PMID 30617282, 2019). "This was accompanied by an increase in breast cancer stemness (SOX2, OCT4, and NANOG levels) and significant increase in the levels of key drug transporters (ABCG2, ABCB1, and ABCC1)." (PMID 31867270, 2019). "This is the case for the mycotoxin zearalenone, identified as an ABCG2 substrate but also as a modulator of CYP1A1 and CYP1B1 activity in a breast cancer cell line." (PMID 31590349, 2019). "In breast cancer cells, silencing of TGF-βRII leads to overexpression of multidrug resistance protein ABCG2 and tamoxifen resistance." (PMID 30065235, 2018). "Many of the genes regulated have previously been shown to correlate with aggressiveness of breast cancer such as CD24, SOX2, Slug, Twist1, CD-133, N-Cadherin, E-Cadherin, FOXC2, ABCG2, c-Myc, IL8, IL6, and IKKβ (activating NF-κB signaling)." (PMID 29552303, 2018). "Some indeno[1,2-b]indole-based CK2 inhibitors additionally obstruct ABCG2, an ABC half transporter overexpressed in breast cancer and co-responsible for drug efflux and resistance." (PMID 29236079, 2017). "ABCG2, which was first named the breast cancer resistance protein (BCRP) for its high expression in an anthracycline resistant breast cancer cell line, is an ABC transporter expressed at the BBB." (PMID 29186899, 2017). "BCRP/ABCG2, an ABC transporter is overexpressed in breast cancer cells and has been shown to be involved in multidrug resistance." (PMID 28261317, 2017).
breast cancer (continued). "In the present study, we determined the promoter methylation patterns of ABCB1, ABCC1 and ABCG2 in human cancer cell lines, MDR cell models and tumor, tumor-adjacent and tumor-distant tissues from breast cancer patients." (PMID 27689338, 2016). "ABCG2 protein is an ATP-binding cassette (ABC) efflux transporter, which was initially cloned from a multidrug-resistant breast cancer cell line and found to confer resistance to chemotherapeutic agents such as mitoxantrone and topotecan." (PMID 27338343, 2016). "Several stemness markers have been described for the various histological subtypes of breast cancer, such as CD44, CD24, CD133, ALDH1, and ABCG2." (PMID 26504780, 2015). "In breast cancer, the expression of stem cell markers such as CD44, ATP-binding cassette sub-family G member 2 (ABCG2) and aldehyde dehydrogenase A1 (ALDHA1) can be used to selectively isolate a cell population enriched in CSC." (PMID 26517518, 2015). "There is a strong correlation between ABCG2 overexpression and development of drug resistance in several cancer cells, including NSCLC, colon carcinoma, hepatocellular carcinoma (HCC) and breast cancer." (PMID 26515463, 2015). "ABCC1, also known as MRP1, is associated with chemotherapy resistance of prostate, breast, and lung cancers, and ABCG2, which is also known as BCRP, is involved in the chemoresistance of breast cancer and leukemia." (PMID 25860815, 2015). "Using pharmacological and molecular approaches, we demonstrated that ABCC1 and ABCG2 (also known as breast cancer resistance protein; BCRP) are involved in estradiol-mediated transport of S1P and dihydro-S1P out of MCF-7 human breast cancer cells." (PMID 25133174, 2014). "ABCG2 is a member of the ABC transporter family, which was first cloned from doxorubicin-resistant human MCF-7 breast cancer cells and was named breast cancer resistance protein (BCRP)." (PMID 24338217, 2014). "In conclusion, our findings provide evidence that selective COX-2 inhibitor celecoxib induces ABCG2 mRNA and protein expression in the sensitive and drug resistant MCF7 breast cancer cell lines." (PMID 25587329, 2014). "Several stemness markers have been described for the various histological subtypes of breast cancer, among them CD44, CD24, CD133, EpCAM, CD166, Lgr5, CD47, ALDH1 and the most recent ABCG2." (PMID 23976904, 2013). "While ABCG2 was originally identified as a multi-drug efflux pump in drug-resistant breast cancer MCF-7/AdrVp cells, recent studies have shown that ABCG2 is an important human uric acid transporter in the kidney." (PMID 24287461, 2013). "They found that side population isolated from prostate cancer, breast cancer and glioma was enriched in tumorigenic, stem-like cancer cells, whereas ABCG2+ and ABCG2− cancer cells were similarly tumorigenic." (PMID 22209971, 2012). "Human ABC transporter ABCG2, originally named Breast Cancer Resistance Protein (BCRP), was first discovered in doxorubicin-resistant breast cancer cells." (PMID 24310600, 2011). "Unlike the study on pancreatic cancer SP cells, it has been shown that in the MCF7 breast cancer cell line, TGFβ induced EMT and depleted the SP population, down-regulated ABCG2 gene expression and increased cell sensitivity to mitoxantrone." (PMID 24212798, 2011). "Many studies have reported increased transcriptional expression of ABCG2 in SP compared to NSP cells in several breast cancer cell lines, and this has been confirmed at the protein level." (PMID 24212798, 2011). "We have recently found that in mitoxantrone (MR)-resistant MCF-7 breast cancer cells (MCF-7/MR), ABCG2 is overexpressed and confined to cell-cell attachment zones, where ABCG2-rich extracellular vesicles (EVs) are formed." (PMID 21283667, 2011). "The growth of breast cancer cell lines in medium containing mitoxantrone resulted in a marked enrichment of cells with CSC-like markers (ALDHhi, c-kit, Oct-4 and ABCG2) and functional characteristics." (PMID 21072210, 2010).
breast cancer (continued). "The ATP-binding cassette membrane transporter ABCG2 (BCRP/Bcrp1) functions as an energy-dependent efflux pump, and was first identified in the breast cancer cell line MCF-7." (PMID 17425799, 2007). "In contrast, another study demonstrated that pharmacological inhibition of p38 enhanced taxane-induced killing in breast cancer cells by promoting chromosomal instability, a mechanism that appears independent of ABCG2-mediated efflux." (PMID 41541684, 2026). "In breast cancer and various other malignancies, PTX and Dox have been reported to enhance the expression of major efflux transporters involved in drug resistance, including P-gp/MDR-1, MRP-1, and ABCG2/BCRP." (PMID 40725123, 2025). "By downregulating key efflux transporters like P-glycoprotein (ABCB1) and BCRP (ABCG2) and modifying chromatin accessibility, HDACis may enhance intracellular drug retention and re-sensitize resistant breast cancer cells to conventional chemotherapeutics." (PMID 40649736, 2025). "Broad substrate specificity ATP-binding cassette transporter G2 (ABCG2), a member of the G subfamily of the ABC protein superfamily, was originally cloned from the anthracycline resistant human breast cancer cell line MCF-7/Adrvp and hence named breast cancer resistance protein (BCRP)." (PMID 40612109, 2025). "Moreover, western blotting analysis revealed an increase in ABCG2 and LC3-II accumulation, as well as a decrease in SQSTM1/p62 expression in breast cancer cells treated with CXCL1 for 24 h." (PMID 39394189, 2024). "Additionally, adriamycin (Dox) induces the upregulation of breast cancer resistance protein (ABCG2) and P-GP in endothelial cells, leading to the increased resistance of breast cancer cells to sunitinib." (PMID 38069225, 2023). "The second member of subfamily G, ABCG2, was originally cloned from a doxorubicin-resistant breast cancer cell line where resistance independent of ABCB1 was strategically sought out by selecting for drug resistance in the presence of a ABCB1 inhibitor." (PMID 37438132, 2023). "Recent studies revealed that NRP-1 could promote breast cancer cells resistance to ADM and PTX resistance through activation of ITGB3/FAK/NF-kB p65 axis and downregulation of BCRP/ABCG2." (PMID 34374639, 2022). "Luteolin is capable of inhibiting the expressions of stem-related transcription factors, the ATP-binding cassette transporter G2 (ABCG2), CD44, the activity of aldehyde dehydrogenase 1 (ALDH1), as well as the spherical-forming properties of breast cancer stem cells." (PMID 35408740, 2022). "The expression of key markers associated with proliferation (MKI67, PCNA, CCNB1, MYBL2, BUB1, CCND1), apoptosis (BCL2, CASP7, CASP8, CASP9, CASP3, BAX, APAF1), differentiation (CDH1, CD24, EPCAM, ESR1, NGFR, RUNX1), and breast cancer stemness (CD44, ITGA6, DNER, ALDH1A3, ABCG2, PROCR) was assessed." (PMID 35183258, 2022). "In a recent study in breast-cancer stem cells, it was reported that chemotherapy enhanced the expression of CAV1 expression in vitro and in vivo, and this was accompanied by co-overexpression of β-catenin and ATP-binding cassette subfamily G member 2 (ABCG2)." (PMID 35158857, 2022). "Importantly, both ABCG2 and ABCC1 were described as MDR mediators in breast cancer at THE clinical level." (PMID 36430819, 2022). "Besides ABCG2, ABCC1 is also frequently overexpressed in breast cancer tissues showing correlation with aggressive phenotype and chemotherapeutic resistance." (PMID 36430819, 2022). "Lapatinib (Tykerb), a dual tyrosine kinase inhibitor that interrupts the HER2/neu and epidermal growth factor receptor (EGFR) pathways, was approved for the use of breast cancer and other solid tumors, and was also shown to inhibit ABCB1- and ABCG2-mediated MDR in cancer cells." (PMID 35327403, 2022). "Consequently, inhibiting ABCC1 or ABCG2 with pharmacological inhibitors decreases estradiol-mediated release of S1P and dihydro-S1P and ERK1/2 activation in breast cancer." (PMID 35565311, 2022).
breast cancer (continued). "Single-cell RNA-Seq analysis conducted with breast cancer CSCs showed a population with hybrid EMT and CSC markers CD44, ABCG2, and ALDH1A1/3, which might mark the MICs." (PMID 34150761, 2021). "Expression of ABCB1, ABCC2, ABCG2, SLC22A16, and SLCO1A2 was significantly higher in normal breast tissue compared to tumorous tissue, while SLC22A1 and the tumor marker ESR1 showed a significantly higher expression in breast cancer tissue." (PMID 35008681, 2021). "Furthermore, apigenin reduces activity of ABCG2 and ABCC4 as drug efflux transporters to enhance internalization of doxorubicin in breast cancer and mediate apoptosis." (PMID 34769099, 2021). "Specifically, ISL chemosensitizes breast cancer stem cells by docking into the adenosine triphosphate (ATP) domain of GRP78 directly, which in turn suppresses β-catenin/ATP-binding cassette subfamily G2 (ABCG2) signaling." (PMID 32164337, 2020). "In summary, only two studies have investigated ABCG2 promoter methylation in breast cancer, with none of them reporting aberrant methylation compared to normal breast cells/tissues." (PMID 33066132, 2020). "Elevated ABCG2 levels have been observed in various hematological malignancies (e.g., acute lymphoblastic leukemia (ALL) and chronic myeloid leukemia (CML)) and solid cancers (e.g., non-small cell lung cancer (NSCLC), ovarian and breast cancer)." (PMID 33066132, 2020). "In the present study, four SNPs of ABC transporter genes, namely ABCC1, ABCC2, ABCB1, and ABCG2, were screened in Jordanian Arabs with and without breast cancer." (PMID 31391850, 2019). "Furthermore, our finding could be supported by a study that reveal how miR-181a can enhances drug sensitivity in BC by targeting breast cancer resistance protein (BCRP/ABCG2)." (PMID 29868122, 2018). "In breast cancer, apart from the capability of elevating the invasive potential, IGF2BP3 was also believed to be involved in chemo-resistance by stabilizing the mRNA of breast cancer resistance protein (ABCG2)." (PMID 28399871, 2017). "In conclusion, in-house developed bisulfite PSQ methods were applied to determine the promoter methylation status of ABCB1, ABCC1 and ABCG2 in 19 human cancer cell lines, MDR cell models as well as tumor, tumor-adjacent and tumor-distant tissues from 16 breast cancer patients." (PMID 27689338, 2016). "In the present study we aimed to enlarge the database by determining the promoter methylation patterns of ABCB1, ABCC1 and ABCG2 in cancer cell lines derived from different types of cancer, MDR cell models as well as tumor, tumor-adjacent and tumor-distant tissues from breast cancer patients." (PMID 27689338, 2016). "More recently, one group from Norway reported on amphiphilic sulfonated photosensitizers that were not effluxed out of breast cancer cells with high ABCG2 expression." (PMID 26714461, 2015). "Among the ABC proteins, the most significant are glycoprotein P (P-gp), encoded by the ABCB1 [multidrug resistance protein 1 (MDR1)] gene, and breast cancer resistance protein (BCRP or ABCG2), which was cloned from a mitoxantrone-resistant subline of the breast cancer cell line MCF-7." (PMID 25574188, 2015). "Because ABCG2 is the primary membrane transporter responsible for drug resistance in breast cancer, our findings implied that the chemosensitizing effects of ISL might be closely correlated with ABCG2 reduction via the autophagy pathway." (PMID 25026296, 2014). "Our findings provide evidence that celecoxib up-regulates ABCG2 expression in human breast cancer cells and proposed that ABCG2 is not involved in chemosensitizing effects of celecoxib." (PMID 25587329, 2014). "The physiological role of the transporter PF14_0244 is not yet clear but the orthologous human ABCG2 transporter is involved in breast cancer drug resistance." (PMID 24146604, 2013).
breast cancer (continued). "And in the area of the mechanism research of breast cancer MDR, our findings pointed out another possible genesis mechanism that hypoxia could induce the expression of ABCG2 by HIF-2α, which promoted the multidrug resistance of breast cancer cells." (PMID 22452996, 2012). "ABCG2 (ATP-binding cassette sub-family G member 2), or breast cancer resistance protein (BCRP), is an vital trans-membrane transporter which plays an important role in the multidrug resistance (MDR) of breast cancer." (PMID 22452996, 2012). "ATP-binding cassette G2 (ABCG2), originally known as Breast Cancer Resistant Protein (BCRP), first discovered in doxorubicin-resistant breast cancer cells is a major member of the ATP-binding cassette transporter family and located on chromosomal region 4q22 encoding a 72-kDa membrane protein." (PMID 22937733, 2012). "Moreover, SALL4 is enriched in SP in breast cancer cell line MCF7 along with ABCA3 and ABCG2, and increased SALL4 expression led to an expansion of SP in MCF7 cells." (PMID 21526180, 2011). "To further investigate if PZ-34 and PZ-38 can reverse ABCG2-mediated MDR in a drug resistant cancer cell line, we used the drug-selected breast cancer cell line MCF7/AdVp3000 which over-expresses ABCG2 and tested an additional anticancer drug substrate of ABCG2, Adriamycin." (PMID 21151870, 2010). "Furthermore, GW2974 reversed ABCG2-and ABCB1-mediated drug resistance in breast cancer cell lines." (PMID 40836976, 2024). "Overexpression of NRP1 in BT-747 breast cancer cells leads to upregulation of the oncogene Tenascin-C and is accompanied by an increase in cellular tumorigenic behavior and downregulated breast cancer resistance protein (BCRP/ABCG2), resulting in enhanced sensitivity to chemotherapy." (PMID 37894289, 2023). "Similarly, the ABCG2-overexpressing S1-MI-80 human colon cancer cells, MCF7-FLV1000 human breast cancer cells, and H460-MX20 lung cancer cells were significantly resistant to HS-173 as compared to the parental S1, MCF7, and H460 cells, with calculated RF values of 10, 12, and 5, respectively." (PMID 37048130, 2023). "MCF7 breast cancer cells that are thought to survive treatment with ionizing radiation (MCF-7/IR6) showed a chemoresistance phenotype by expressing high levels of MDR1 (ABCB1) but not of MRP1 (ABCC1) or BCRP (ABCG2)." (PMID 35215350, 2022). "ABCG2 (also known as the breast cancer resistance protein – BCRP) plays a pivotal role in drug resistance (e.g. anthracyclines and topoisomerase inhibitors) and as important marker of side population cells, which are enriched for cells with CSC characteristics in breast cancer." (PMID 33167919, 2020). "The role of the ATP-binding cassette (ABC) transporters in tumorigenesis of White breast cancer patients is further supported by the enrichment of the “brown” module in basal transcription factors, including the ATP-binding cassette subfamily members ABCA9, ABCC9, ABCG2, ABCB1, ABCA6, and ABCA8." (PMID 32873298, 2020). "In addition, some studies point out that the up-regulation of EMT-associated transcriptional factors, containing Slug, Zeb1 and Twist1, can directly lead chemotherapy in breast cancer and NSCLC through the ATP-binding cassette (ABC) transporter family of proteins (ABCB1, ABCC1 and ABCG2)." (PMID 33282725, 2020). "Exosomal ABCG2 expression can be induced by the phosphoinositide-3-kinase–protein kinase B (PI3K)- protein kinase B (Akt) signaling pathway and inhibition of this pathway led to cytoplasmic re-localization of ABCG2 and increased drug sensitivity in breast cancer cells." (PMID 30925921, 2019). "It is also uncertain whether or not the ABCG2 inhibitor is invariably essential for PpIX‐based discrimination of human breast cancer cells." (PMID 31385432, 2019).